HMGB1 (high mobility group box 1)
Diseases named in the same sentence as HMGB1 in open-access papers (continued):
Sharing a sentence is not in itself a finding about the gene and the disease.
tumor (continued). "The release of immunostimulatory components such as High Mobility Group Box 1 (HMGB1) and adenosine triphosphate (ATP) activates dendritic cells and effector T cells, which in turn increase the body’s anti-tumor abilities." (PMID 36761954, 2023). "RAGE, HMGB1, and S100A8/A9 are critical molecules for MDSC development and function, but they also have other mechanisms by which they promote tumor growth." (PMID 36831371, 2023). "Previous reports using murine models have shown that TKIs prompt tumor cells to release chemotactic factors (CXCL12 and HMGB-1) or induce immunogenic cell death, resulting in robust immune cell infiltration and tumor clearance." (PMID 36839733, 2023). "Consistently, RA‐biotin‐captured TDP‐43 and RA‐induced HMGB1‐Gluc activity were dramatically reduced in CRISPR‐Cas9‐engineered TDP‐43KO tumor cells." (PMID 36876644, 2023). "We validated our RNA-sequencing results by performing IHC on day fourteen tumor sections for markers of cell death (cleaved caspase-3) and DAMP release (HMGB1 or calreticulin)." (PMID 37090639, 2023). "The authors showed that HMGB1 is an endogenous agonist for TLR2, which is released from dying tumor cells in response to radiation or other stress-inducing agents (e.g., temozolomide)." (PMID 37112730, 2023). "The HMGB1 1177G/C genotype was detected in OSCC and suggested as a potential marker of tumor stage and progression." (PMID 37511951, 2023). "Moreover, tumor-associated autophagy is closely related to tumor resistance to immune surveillance, in which TME components, such as Tregs and MDSCs, have a key role in the tumor escape phenomenon, while their survival is closely associated with HMGB1-induced autophagy." (PMID 36833401, 2023). "Taken together, these data indicate that OVesRAGE virus inhibits oHSV therapy-induced HMGB1-RAGE signaling in the TME, thereby allowing increased virus spread and enhancing anti-tumor efficacy in vivo." (PMID 36789106, 2023). "The benefit of anti-HMGB1 antibody treatment on tumor progression is diminished by prior MDSC depletion, demonstrating that MDSCs are the dominant targets for HMGB1." (PMID 36831371, 2023). "In this respect, the released HMGB1 plays a critical role in regulating the epithelial mesenchymal transition (EMT), which initiates tumor invasion and metastasis." (PMID 37210579, 2023). "Circ_0067934 reduced tumor cell ferroptosis via modulating miR-545-3p/SLC7A11 pathway and promoted tumor progression via miR-1301-3p/HMGB1 in thyroid cancer." (PMID 38152652, 2023). "In the tumor array, correlations were observed between S100A9 and S100A8 (R = 0.62), S100A4 (R = 0.78), S100A10 (R = 0.51), S100A12 (R = 0.76), and HMGB1 (R = 0.80)." (PMID 37627239, 2023). "Collectively, our findings implied that HMGB1 overexpression probably exerted a drug resistant role and malignant development promoting role in NSCLC via the altered cell localization in tumor cells." (PMID 37518006, 2023). "S100 proteins and high-mobility group box 1 (HMGB1) are expressed and secreted by different tumor cells." (PMID 36652782, 2023). "Once RAGE is engaged by HMGB1, several signaling pathways such as MAPK and NF-KB become activated, thereby reprogramming cellular properties and progress to tumor migration and proliferation." (PMID 37210579, 2023). "The interaction between extracellular HMGB1 and TLR4 correlates with ICD, and the depletion of TLR4 and the depletion or neutralization of HMGB1 can eliminate the cross-presentation of tumor antigens by DCs." (PMID 36906586, 2023). "Existence of AGEs in the tumour milieu initiates a signalling cascade which activates RAGE and augments the expression of DAMP molecules/pro-inflammatory ligands—HMGB1 and S100 family of proteins, by prompting the binding of AP-1 to HMGB1/S100 promoters." (PMID 37970208, 2023).
tumor (continued). "GRh2 is obtained from the roots of P. ginseng and has been reported to have anti-tumor effects by immunomodulating the tumor microenvironment (TME), regulating HMGB1/NF-κB signaling, and improving the oxygen–glucose deprived environment of cardiomyocytes." (PMID 38139116, 2023). "Cryosurgery induces ICD, leading to the expression of DAMPs like HMGB1, CRT, HSP-70, and HSP-90 and maturation of DCs, which activates CD8+ T cells to attack tumor cells." (PMID 36693842, 2023). "The interaction between HMGB1 and RAGE has been suggested to promote the proliferation and invasion of various tumor cells." (PMID 38132142, 2023). "The binding of extracellular HMGB1 to TLR4 inhibits the fusion between phagosomes and lysosomes, which is involved in the cross-presentation of tumor antigens by DCs." (PMID 36949244, 2023). "This sustenance of inflammatory tumour micro-milieu is facilitated by AGE-RAGE and HMGB1/S100-RAGE signalling." (PMID 37970208, 2023). "CMS5 tumor cells are more sensitive to the MMC treatment, as evidenced by a higher proportion of calreticulin and HMGB1-positive cells, compared to E.G7 tumor cells, which are more likely to undergo immunogenic cell death." (PMID 37631898, 2023). "While the multiple activities orchestrated by CXCL12 in the tumor microenvironment have been well documented, as well as the presence of HMGB1, little is known on the relevance of the CXCL12/HMGB1 heterocomplex in mediating tumor growth and metastasis." (PMID 37251376, 2023). "It has been shown that CLL cells promote NLC differentiation in the tumor microenvironment by releasing soluble factors such as nicotinamide phosphoribosyl transferase (NAMPT) and the nuclear protein high-mobility group protein B1 (HMGB1)." (PMID 37958334, 2023). "In this study, we demonstrated that the extracellular HMGB1 protein, recognized as a DAMP in the tumor microenvironment, plays a critical role in tumor angiogenesis and development." (PMID 37210579, 2023). "UTMD alone or combined with Dox mediated the release of DAMPs (such as HMGB-1, HSP, ATP) from tumour cells." (PMID 36463323, 2023). "The MDSCs also expressed RAGE, HMGB1, and S100A8 and A9 transcripts and Western blots confirmed the presence of the corresponding proteins, although only tumor-induced MDSCs contained S100A8/A9 heterodimers." (PMID 36831371, 2023). "The ELISA results illustrate the robust induction of IL-1β, IL-18 and HMGB1 production, an indicator of pyroptosis-induced ICD, in both tumor and serum samples following treatment with GSDMBNT mRNA@LNPs alone or in combination with a-PD1." (PMID 37454146, 2023). "When VEGF and VEGF-C were investigated as major ligands of RAGE upon human recombinant HMGB1 administration in OSCC cell lines, it was shown that VEGF secretion was significantly upregulated in RAGE-positive tumor cells in a dose-dependent manner." (PMID 37511951, 2023). "HMGB1 upregulation and the successive overexpression of IL-23, IL-17 and IL-6, followed by STAT3 activation, promotes tumor growth." (PMID 37772080, 2023). "Since related studies have shown that radiotherapy can promote immunogenic death of tumor cells, immunogenic death can be observed by detecting CRT and HMGB1." (PMID 37438720, 2023). "Hypoxia also increases HMGB1 release and RAGE expression in the tumor microenvironment, inducing the expression of proangiogenic growth factors, such as vascular endothelial growth factor (VEGF), and their receptors." (PMID 37110415, 2023). "Compared with SC144 treatment, SC144@HABN treatment significantly elevated the serum concentrations of HMGB-1 and CXCL-10 (p < 0.05) and increased CRT levels in CD45- tumor cells (p < 0.001)." (PMID 37553327, 2023). "In summary, circMMP11 shows promise as a diagnostic biomarker target and a valuable therapeutic target for HCC as it plays an anti-tumor role by suppressing proliferation, migration, and invasion in HCC, possibly through the miR-361-3p/HMGB1 axis." (PMID 38025527, 2023).
tumor (continued). "The tumor weights in the 3-OBA and HMGB1 groups were prominently lower than those in the control group." (PMID 36709284, 2023). "In unilateral 4T1 tumor‐bearing model, MON‐PpIX‐LA‐CO2+US (twice) group achieved higher level of TAAs exposure and DAMPs (CRT, HSP70 and HMGB1) than control group." (PMID 36437106, 2023). "The study showed that T cell accumulation/activation at the tumor site activated caspase 3 and GSDM E cleavage, favoring the release of HMGB1 and PYR induction." (PMID 36674798, 2023). "These nanoparticles played the role of antioxidants to remove extracellular ROS before entering the lysosomes of tumor cells, and they enhanced the ICD induced by PDT and ferroptosis through activating HMGB1." (PMID 37894410, 2023). "We and others have previously identified that oHSV infection triggers the release of a high-mobility group box 1 (HMGB1) secretion into the TME, and this results in increased tumor edema that can limit oHSV efficacy." (PMID 36789106, 2023). "As HMGB1 can act as a damage associated molecular pattern in the extracellular space to modulate immune responses, we next focused our attention back to the CRC TMA (n = 650) to assess whether epithelial HMGB1 expression was associated with the tumour immune microenvironment." (PMID 36980751, 2023). "Radiotherapy (RT) has been shown to trigger immunogenic cell death with HMGB1 (High Mobility Group Box 1) release by tumor cells and dendritic cells (DCs) activation through TLR4, allowing a tumor antigen-specific T cell immunity." (PMID 37946136, 2023). "GL is one of the most potent inhibitors of HMGB1 and is known to block the nucleocytoplasmic translocation of HMGB1, thereby inhibiting its extracellular secretion and function as a DAMP in the tumor microenvironment." (PMID 37210579, 2023). "Therefore, inhibition of STAT1/HMGB1 may enhance cisplatin chemotherapy in tumors and protect kidneys from chronic nephrotoxicity, an intriguing possibility that requires further tests in tumor-bearing animal models." (PMID 37284446, 2023). "Mice in the anti-HMGB1 mAb group (labeled EC18H + B + αHMGB1 in green) and GL group (EC18H + B + GL in purple) had smaller tumor volumes and weights in comparison to their control tumors (labeled EC18H + B in black)." (PMID 34617194, 2022). "At first, the HMGB1 expression in HCC cells and immortalized hepatocytes was examined by western blot, showing the elevated expression of HMGB1 in tumor cells." (PMID 35562734, 2022). "Combined HMGB1 and p-ATM, the results showed patients with both positive expression of HMGB1 and p-ATM have larger tumor and more distant metastasis than those with single positive/double negative expression of HMGB1 and p-ATM." (PMID 36260180, 2022). "Briefly, tumor cells undergoing ICD expose calreticulin (CRT) on the outer leaflet of the cell membrane, secreting adenosine triphosphate (ATP) and releasing high mobility group box 1 (HMGB1) into extracellular microenvironment." (PMID 36341334, 2022). "When the nanocomposites were internalized by tumor cells, DOX promoted tumor cells to secrete CRT, HMGB1 and ATP as danger signals to stimulate antitumor immune responses, while CpG acted as a powerful promoter." (PMID 35652198, 2022). "Third, the release of DAMPs including ATP, HMGB1, HSP70, and calreticulin from tumor cells are vital for inducing ICD." (PMID 35740542, 2022). "For example, HMGB1 acts through TLR4/TLR9 receptors and activates tumor cells via the p38/NFkB pathway." (PMID 36555469, 2022). "Evidence indicates that TAB are able to negatively modulate the tumor-immune microenvironment mainly by upregulating the expression of transforming growth factor beta 1 (TGF-β1) and high mobility group box 1 (HMGB1) proteins in tumor cells." (PMID 36381212, 2022).
tumor (continued). "Kramer-Marek conducted photoimmunotherapy by conjugating an EGFR-specific affibody molecule to IR700, which generated ROS; induced ICD with the release of HMGB1, CRT, ATP, and HSP70/90; and promoted an anti-tumor immune response in a murine model." (PMID 36145510, 2022). "Among the currently available HMGB1-related combination therapy strategies, the most frequent is the employment of ICD inducers to activate adaptive anti-tumor immune responses in patients." (PMID 35637945, 2022). "S100-derived peptide (ELKVLMEKEL) was found to compete for the RAGE site required to bind ligands, such as S100P, S100A4, and HMGB1, and reduced RAGE-mediated NF-κB activation, inflammation, tumor growth, and metastasis in different cancer cells." (PMID 35956875, 2022). "The release of large amounts of DAMPs from necrotic tissue further affect tumor microenvironment, including RNA, DNA, HSP-70, HSP-90, High Mobility Group Protein B1 (HMGB1), C-reactive protein and uric acid, which is similar to cryoablation." (PMID 36131929, 2022). "HMGB1 combined with TIM-3 induces the secretion of VEGF, promoting tumor angiogenesis, which is the first step toward the metastasic process." (PMID 36012593, 2022). "We observed the dramatic increase of HMGB1 excretion and CRT exposure in tumor tissues treated with PEG-MP9-aPDL1 than other groups." (PMID 35547769, 2022). "So far, the combination strategies like PDT synergized with chemotherapy or photothermal therapy (PTT) have been developed for increased tumor ICD 21, whose characteristics are to expedite antigen presentation via CRT exposure, HMGB1 release and ATP secretion." (PMID 35910806, 2022). "Since the release of HMGB1 plays an important role in shaping the tumor immune microenvironment, it is also expected that XPO1 can promote the translocation and release of HMGB1 in cancer." (PMID 35217834, 2022). "Under the synergistic effect of Zn and 5-Fu, those tumor cells, treated with Zn-Fu MNs, released various antigens such as CRT, HMGB1 and ATP, which would enhance the activation of immune cells." (PMID 36168615, 2022). "Furthermore, the discrete effect observed with respect to increased tumor growth and weight in mice injected with CM from co-culture with HMGB1-expressing tumor cells, highlighting that secretion of mediators between B cells and tumor cells could promote an overall effect on tumor progression." (PMID 34617194, 2022). "At the same time, HMGB1 increases the amount of CD8+ TILs and also participates in the processes of tumor cell death through the activation of innate and adaptive antitumor immune reactions." (PMID 36140182, 2022). "In vitro, the expression of HMGB1 and HSP70 was increased in 4T1 cells infected with AdVEGFR2, which was responsible for the activation of tumor antigen-specific T cell immunity." (PMID 35637945, 2022). "Recombinant NDV NDV-MIP3α expressing the macrophage inflammatory protein-3α (MIP3α), a chemokine of DCs, exhibited tumor killing and ICD initiation, same as the wild-type NDV via HMGB1 and ATP release." (PMID 36755812, 2022). "In tumour cells, TRAIL stimulates PARP-1 activation and subsequently the PARylation of high-mobility group box protein 1 (HMGB1) which results in HMGB1 localisation to the cytoplasm." (PMID 36159999, 2022). "We revealed for the first time that SEMA3B-AS1 can bind HMGB1 to promote the transcription and expression of FBXW7, thus exerting its tumor suppressive effect." (PMID 35273678, 2022). "Finally, because 2D cell cultures have limitations that might impact the response to anticancer agents, we evaluated the capability of both HMGB1-fl and HMGB1-ΔC to inhibit the growth of 3D tumor cell spheroids which are believed to more closely mimic in vivo conditions." (PMID 35887213, 2022). "In parallel, RT-qPCR detection demonstrated the transcription levels of CHMP4A, HMGB1 and PLK1 were increased in tumor tissues compared to normal ones." (PMID 36267972, 2022).
tumor (continued). "The activation of the HMGB1:RAGE axis increases miR-221 and miR-222 expression in thyroid cancer cells, thereby facilitating tumor progression." (PMID 35269471, 2022). "Therefore, 3-D cultures, which better mirrors the in vivo tumor microenvironment in terms of cellular heterogeneity, nutrient and oxygen gradients, cell-cell interactions, and matrix deposition, is the method of interest to explore the effect of extracellular HMGB1." (PMID 35610613, 2022). "rVSV-NDV induced tumor-specific syncytia formation, followed by dynamic cell-to-cell virus transmission for rapid onset of ICD in HCC, as observed by ATP, HMGB1, Hsp70, and Hsp90 release and CRT expression." (PMID 36755812, 2022). "TGF-β1 and HMGB1 proteins are closely related to the proliferation and metastasis of cancer cells, and secretory TGF-β1 from tumor cells can inhibit the response of immune cells including DCs and macrophages in TME." (PMID 36381212, 2022). "Tumor growth in HFD-fed obese mice had higher circulating dsDNA and citrullinated histone H3, plasma HMGB1, tumor contents of HMGB1, citrullinated histone H3, neutrophil elastase, PAD4 and MPO when compared to tumors in ND-fed lean mice." (PMID 36012397, 2022). "CRT, HMGB1, and other ICD-related DAMP levels were significantly increased compared to those achieved with radiotherapy alone, tumor cell growth was inhibited, and the tumor-killing effect was enhanced considerably." (PMID 36466838, 2022). "Direct treatment of tumor cells with CAP can alsotrigger ICD by inducing the exposure of calreticulin and HSP70 on the outermembrane, as well as secretion of ATP and HMGB1." (PMID 35441043, 2022). "Then, HMGB1 and mtDNA can activate endosomal TLR9, leading to tumor progression in a feedback mechanism." (PMID 35565420, 2022). "It is widely acknowledged that platelets can be activated by various factors released by tumor cells like TF, adenosine diphosphate (ADP), thromboxane A2 (TXA2) and high-mobility group box 1 (HMGB1)." (PMID 35494001, 2022). "A wide range of immune deconvolution methods were applied to investigate the correlation between HMGB1 expression and the immune infiltration level of CD8+ T‐cells in 33 tumours." (PMID 35765707, 2022). "Cancer cell-derived HMGB1 can modulate platelet-resident TLR4 receptors, thereby increasing platelet-dependent tumor metastasis." (PMID 35574410, 2022). "It was shown that HMGB1 induces proliferation of tumor cell and expression of PCNA through ERK1/2 pathway to promote the occurrence of IBD-related CRC, while GSDME-mediated pyroptosis can release HMGB1." (PMID 36092900, 2022). "FAP, also found abundant in CAFs, was recently shown to mediate immunosuppression in a transplanted murine tumour model, while the release of the DAMP, high-mobility group protein B1 (HMGB1), plays a key role in sustained inflammatory signalling." (PMID 36293328, 2022). "Tumour ICD, including by RT, also results in the release of high‐mobility group box protein 1 (HMGB1) and heat shock proteins (HSP) as well as accumulation of fragmented DNA in the cytoplasm of tumour cells." (PMID 35261190, 2022). "For instance, HMGB1 promotes the invasion and migration of tumor cells for KIRC, and there is a significant relationship between HMGB1 expression and poor clinical prognosis." (PMID 36230798, 2022). "Radiotherapy can lead to ICD and the release of high migration group box 1 protein (HMGB-1); HMGB-1 binds to Toll-like receptor-4 (TLR-4), participates in the progression and presentation of tumor antigens, and promotes the activation and maturation of DCs." (PMID 35935943, 2022). "HMGB1 was originally described as a nuclear protein; extracellular HMGB1 is recognized as a prototypical DAMP, which promotes tumor progression." (PMID 34617194, 2022).